RN7SL801P (RNA, 7SL, cytoplasmic 801, pseudogene)
Gene: Miscellaneous RNA gene on chromosome 5 (54,048,007 to 54,048,308, reverse strand). Ensembl gene ENSG00000241230.
Homologues: Orthologues: chimpanzee Metazoa_SRP (98% identical), macaque Metazoa_SRP (79% identical). Paralogues in human: RN7SL1 (79% identical), RN7SL2 (79% identical), RN7SL296P (78% identical), RN7SL3 (78% identical), RN7SL44P (77% identical), RN7SL45P (77% identical), RN7SL597P (77% identical), RN7SL786P (77% identical), RN7SL566P (77% identical), RN7SL478P (77% identical), RN7SL507P (77% identical), RN7SL543P (77% identical), and 701 more.